MUC5AC (mucin 5AC, oligomeric mucus/gel-forming)
Diseases named in the same sentence as MUC5AC in open-access papers (continued):
Sharing a sentence is not in itself a finding about the gene and the disease.
colon carcinoma (38 papers, 2008 to 2025). "A total of 13 studies have earlier analyzed the relationship of MUC5AC expression and tumor location in colon cancer, and almost all of them (11/13) have found a significant association of MUC5AC expression with proximal cancers." (PMID 33373033, 2021). "Apart from MUC2, LS174T cells also secrete MUC5AC, which is usually expressed in the stomach but also associated with colon cancer." (PMID 28054754, 2017). "Increased expression of MUC5AC has been associated with a poor prognosis in some cancers (including uterine, small bowel, and KRAS-mutant lung cancers), whereas expression of MUC5AC has been potentially linked with an improved prognosis in gastric, ovarian, and colon cancers." (PMID 36672382, 2023). "None of the earlier studies on the putative clinical role of MUC5AC expression in colon cancer have considered the association between MUC5AC expression and clinic-pathological parameters in the subgroups of mismatch repair proficient (pMMR) and dMMR cancers in their analyses." (PMID 33373033, 2021). "High secretion of MUC5AC is associated with colon cancer compared with rectal cancer." (PMID 31933627, 2019). "This study aimed to investigate the effect of 8 weeks of quercetin supplementation combined with intermittent exercise on the protein levels of intestinal Muc5Ac, Muc4, and polyphosphate in rats with chemically induced colon cancer." (PMID 40969596, 2025). "Other mucins, such as MUC1, MUC2 and MUC5AC, are rarely expressed in normal tissues but are expressed in the early stages of lung cancer, breast cancer, and colon cancer." (PMID 38702644, 2024). "Altogether, these data demonstrate that colonic cancer cells produce higher levels of MUC5AC in response to chemotherapy treatment, which form a barrier that protects cells from incorporation of extracellular compounds." (PMID 35131032, 2022). "At least 9 studies have analyzed MUC5AC expression and dMMR/MSI in colon cancer, and all of them have described significant associations." (PMID 33373033, 2021). "Since chronic UC can develop into colon cancer, they propose MUC5AC as a surveillance biomarker for the progression of UC." (PMID 33946184, 2021). "MUC5AC promotor hypomethylation results in MUC5AC upregulation and was shown to be associated with a “mutator” phenotype in—especially MSI—colon cancers." (PMID 33373033, 2021). "We initially analyzed The Cancer Genome Atlas (TCGA-COAD) database containing 287 colon cancer and 41 normal samples for MUC5AC expression and observed a significant (p < 0.05) up-regulation of MUC5AC in colon cancer patients." (PMID 32098629, 2020). "A previous study showed that FUT1 overexpression in colon cancer cells catalyzed the addition of α1,2-fucose to MUC5AC, indicating the implication of FUT1 in the glycosylation of MUC5AC26." (PMID 32332708, 2020). "Intestinal MUC5AC is usually expressed in small pit cells that secrete mucus in the stomach glands, but expression in colonic tumors cells depends on culture conditions." (PMID 30813459, 2019). "Surprisingly, human pathologies such as colon cancer and ulcerative colitis produce MUC5AC de novo, which is then secreted." (PMID 23741618, 2013). "MUC5AC, one of the gastric mucins, is closely associated with MSI-H colon cancer." (PMID 41458856, 2025). "In human colonic cancer cells (HT29-18N2), TRPM5 channels have the potential as pharmacological targets for managing mucus-associated pathologies, such as cystic fibrosis, given their roles in regulating Ca2+-mediated mucin 2 and MUC5AC secretion." (PMID 38188686, 2023). "RELMβ enhances MUC2 and M1/MUC5AC gene expression in human colon cancer cells." (PMID 36691020, 2023). "MUC5AC has been used for detecting xenografts of human colon cancer lines via MRI." (PMID 36900282, 2023). "Similarly, in the case of colon cancer, loss of MUC2 and MUC4 and gain of MUC5AC and MUC16 expression have been reported temporally with oncogenic progression." (PMID 36980526, 2023).
colon carcinoma (continued). "Given the well-known associations of MSI with right-sided colon cancer location, it was expected that MUC5AC (as any biomarker) would be linked to both or none." (PMID 33373033, 2021). "Our data demonstrate a striking link of MUC5AC expression with right colon tumor location and dMMR." (PMID 33373033, 2021). "In addition, Sh5AC cells showed less cell proliferation, invasion, and migration compared with Scr cells, which suggests that MUC5AC impacts in vitro colon cancer cell growth, migration, and invasion properties." (PMID 32098629, 2020). "However, in light of the frequently observed aberrant mucin profile in certain colon cancer subtypes, the regulation of other mucins such as MUC5AC has also been studied." (PMID 32168759, 2020). "However, MUC5AC expression is unrelated to colon cancer aggressiveness." (PMID 33373033, 2021). "Our aim was to study whether MUC5AC had a role in colon cancer progression." (PMID 32098629, 2020). "However, the elevated MUC2 expression (positive vs. negative: OR = 1.64, 95% CI = 1.01–2.67, P = 0.04) and MUC5AC expression (positive vs. negative: OR = 1.97, 95% CI = 1.48–2.62, P < 0.00001) were associated with colon cancer." (PMID 31933627, 2019). "When evaluating new biomarkers for colon cancer, MUC1, MUC2, MUC4, MUC5AC, and MUC6 are currently documented in the largest bodies of work regarding their role in the progression from normal colonic tissue to malignancy." (PMID 36900282, 2023). "The results in the human colonic cancer goblet cell line (HT-29-18N2) showed that TRPM4 protein controls calcium-mediated secretion of MUC2 and MUC5AC in conjunction with a Na+/Ca2+ exchanger NCX." (PMID 35158942, 2022). "In addition, the possible targeting factors of NOTCH3 and SMARCA4 in colon cancer cells were screened through RNA‐seq, and, for the first time, we identified that MUC5AC and MUC2 may be the targeted factors for the co‐regulation of NOTCH3 and SMARCA4 interaction." (PMID 35900231, 2022). "Further prospective studies evaluating adjuvant chemotherapy in stages II and III colon cancer should include MUC2, MUC5AC, and MUC6 expression analysis for patient stratification." (PMID 27298226, 2016). "For example, mucin 5AC (MUC5AC) mRNA was increased 582-fold in SSA/Ps by RNA-seq and has been reported to have increased expression in colon cancers." (PMID 24533081, 2014). "siRNA-mediated knockdown of 7343 human gene products in a human colonic cancer goblet cell line (HT29-18N2) revealed new proteins, including a Ca2+-activated channel TRPM5, for MUC5AC secretion." (PMID 23741618, 2013). "In this work we addressed the following 4 questions: Does γ-secretase inhibition modify the differentiation pattern of colonic cancer cells that are constitutively committed to differentiate into mucus-secreting (MUC2, MUC5AC) or enterocytic cells?" (PMID 23409082, 2013). "Studies on the immunohistochemistry of colon cancer also revealed that the low expression of MUC2 is associated with colon tumor and less favorable disease outcome, and lack of expression of MUC5AC and MUC6 were associated with worsened stages of CRC." (PMID 40699805, 2025). "Colonic carcinomas with MUC2-positive and MUC5AC-negative were increased the risk of the nodal metastasis, leading to a poor prognosis." (PMID 33452648, 2021). "It is worth investigating the influence of MUC5AC on the pancreas’s microenvironment and vice versa, and the impact of such influence on carcinogenesis.NPC-1C and PAM4 Mabs failed to have a meaningful impact in treating pancreatic and colon cancers." (PMID 34205412, 2021). "In normal physiological conditions, secretory mucin MUC5AC is not expressed in the colonic mucosa, whereas its aberrant expression is observed during development of colon cancer and its precursor lesions." (PMID 32098629, 2020).
colon carcinoma (continued). "MUC5AC, which is a product of normal gastric mucosa, is absent from normal colon but frequently present in colorectal adenomas and colon cancers, and expressed in patients with ulcerative colitis." (PMID 19088856, 2008). "However, such inhibition was observed only with pancreatic and colon tumor cell lines and was not seen with lung cancer cell lines (which express native MUC5AC) or squamous cell lines." (PMID 34205412, 2021). "Up to now the impact of γ-secretase inhibitors on the differentiation of colonic cancer cells has been evaluated only on the basis of MUC2 gene expression, without taking into account the fact that colonic cancer cells ectopically express the MUC5AC gastric mucin." (PMID 23409082, 2013).
dry eye (36 papers, 2010 to 2025). "It is feasible that H3 variants provide a protective function against ocular disease because MUC5AC expression has been previously associated with dry eye syndrome." (PMID 38991590, 2024). "Tear biomarker MUC5AC, a gel-forming mucin secreted by conjunctival goblet cells, has been investigated as a potential diagnostic tool for SS-related dry eye." (PMID 39408709, 2024). "Every form of dry eye, but also atopic keratoconjunctivitis, is associated with ocular inflammation, loss of goblet cells and reduced levels of MUC5AC." (PMID 32717869, 2020). "Dry eye is associated with reduced concentration of MUC5AC as well as reduced glycosylation of the MUC5AC and MUC16 molecules." (PMID 32717869, 2020). "Although we could not demonstrate whether the decrease in GCD and MUC5AC directly caused dry eye, one study suggested a correlation between MUC5AC expression and dry eye clinical test results such as tear break up time." (PMID 32873276, 2020). "Nevertheless, a subsequent study confirmed the correlation between conjunctival lissamine green staining and SS dry eye diagnosis and found that a significant reduction in tear MUC5AC was accompanied by increased tear IL-8 levels in SS patients." (PMID 39408709, 2024). "Collectively, these findings emphasize the significance of MUC5AC in maintaining tear film integrity and its potential as a relevant biomarker for conjunctival goblet cell function and SS-related dry eye." (PMID 39408709, 2024). "Mucins have altered production and expression in dry eye syndrome with studies using a MUC5AC knock out mouse model to simulate dry eye disease in animals." (PMID 38756167, 2024). "The functions of the gel-forming mucins are derived from studies that focused on MUC5AC (e.g., a MUC5AC knockout mouse model, serving as dry eye model), which is the most prevalent secreted mucin at the ocular surface and a well-known goblet cell marker." (PMID 34638869, 2021). "AQP5 highly expressed in lacrimal and salivary gland was reported to be lowered in a rabbit model of dry eye and the interaction between MUC5AC and AQP5 was pointed out." (PMID 32437405, 2020). "Kojima and colleagues recently reported that hylan A containing eye drops, but not LMW HA containing eye drops preserve the tear volume and Muc5AC secretion under environmental stress in a mouse dry-eye model." (PMID 32717869, 2020). "Though not supported by clinical signs and symptoms, lowered GCD and lowered MUC5AC indicates dry eye in DM cases who underwent VR surgery especially in the vitreous hemorrhage, non-suture and conjunctival non-opening group." (PMID 32437405, 2020). "Many studies have reported significantly decreased MUC5AC secretion by goblet cells in patients with dry eye." (PMID 32437405, 2020). "First such clues were provided by animal models of dry eye that employ chronic exposure to the anti-cholinergic agent scopolamine to reduce goblet cell secretion of MUC5AC." (PMID 31817367, 2019). "Subsequently multiple evidences were found in biochemistry studies that the amount of MUC5AC decreases up to three times in dry eye patients and the degree of O- and N-glycosylation is also altered in DES sufferers compared to healthy individuals." (PMID 31817367, 2019). "Whereas α-MSH restored both parameters of goblet cells in the dry eye rats to the normal levels, indicating the normalized MUC5AC content and the improved tear film stability under dry eye condition." (PMID 26685899, 2015). "Expressions of MUC1, MUC2, MUC4, and MUC5AC are significantly lower in conjunctival epithelium gathered by impression cytology in the patients with dry eye syndrome compared with that in normal subject." (PMID 26818460, 2015). "Using Schirmer strip samples, mean MUC5AC content in tears was found to be lower in the dry eye patients than in the age- and gender-matched healthy individuals." (PMID 26605353, 2014).
dry eye (continued). "Most recently, Konat Zorzi et, al. has carried out a proof-of-concept experiment, in which nanoparticles are used to deliver MUC5AC expression plasmid into ocular surface epithelial cells to treat dry eye syndrome." (PMID 23272068, 2012). "Muc5ac has been shown by both us and others to be downregulated in the dry eye from Sjogren syndrome." (PMID 23272068, 2012). "In dry eye patients with Sjögren's syndrome, a significant decrease in the expression of MUC5AC mRNA and MUC5AC protein has been reported, suggesting that MUC5AC is important in preventing drying diseases of the ocular surface." (PMID 22065934, 2011). "Because tear film instability is considered to be one of the key factors of dry eye (DE), CGCs and MUC5AC have drawn wide attention in DE studies." (PMID 21031014, 2010). "Interestingly, the Osaka cross-sectional study revealed low mean tear mucin 5AC (MUC5AC) concentrations in the early stages of dry eye in young VDT workers." (PMID 40056354, 2025). "Additionally, the upregulation of Muc5AC by CsA was also observed in dry eye patient with chronic graft-versus-host disease." (PMID 40178682, 2025). "A decrease in MUC5AC secretion has been reported in patients with dry eye." (PMID 36830824, 2023). "Further studies are required to determine whether the mRNA level of MUC5AC could serve as a marker to characterize dry eye severity and progression in VDT users." (PMID 37106448, 2023). "Specifically, immunoblotting against AQP5 and MUC5AC in the total protein homogenates isolated from the rabbit conjunctiva showed a positive and synchronous expression pattern with progressive upregulation in dry eye mice models." (PMID 36077012, 2022). "Based on our results and those of previous studies, severe allergic inflammation stimulated by allergen exposure on the ocular surface might decrease the number of goblet cells, and a reduction in MUC5AC secretion could elicit dry eye-like clinical findings." (PMID 34194821, 2021). "Use of PI may be a pathogenic factor causing postoperative dry eye resulting from the decrease in GCD and MUC5AC stain." (PMID 32873276, 2020). "Hyaluronic acid (HA) has been commonly used in eyedrop formulations due to its viscous lubricating properties even at low concentration, acting as a supplement for ocular mucin (principally MUC5AC) which diminishes with aging in a condition known as Keratoconjunctivitis sicca or “dry eye”." (PMID 33023220, 2020). "Because Muc5ac knockout mice have clinical features of dry eye, this mouse model will be extremely useful for further studies regarding the pathophysiology of the ocular surface in dry eye in humans." (PMID 23272068, 2012). "Both the number of goblet cells and the secretory volume of MUC5AC remained at low levels for 3 weeks after dry eye was induced in the model animals; the diminished secretion state in the goblet cells did not display any recovery after BAC was no longer administered." (PMID 22438984, 2012). "Furthermore, the bulbar conjunctival lissamine green staining score was found to be significantly greater in SS dry eye patients than in non-SS dry eye patients, and greater conjunctival staining was associated with a reduction in tear MUC5AC." (PMID 40095328, 2025). "The association between reduced MUC5AC and the severity of dry eye or underlying SS remains unclear, due to the absence of a non-SS dry eye control group." (PMID 39408709, 2024). "Furthermore, the instillation of 3% diquafosol ophthalmic solution had immediate (within 15 min of instillation) TF stabilizing effect in keratoconjunctivitis sicca rat models which precisely matched the time course of the drug induced increase in the secretion of MUC5AC in tears." (PMID 31817367, 2019). "It has been shown that dry eye-related inflammatory mediators (TNFα, IL-1β, IL6/IL17, and prostaglandin E2) upregulate MUC5AC mRNA expression." (PMID 36209216, 2022).
dry eye (continued). "In this study, we investigated the utility of the ocular surface test, which clinically evaluates mucin-related gene (SPDEF, MUC5AC, and MUC16) expression levels on the ocular surface in patients with dry eye." (PMID 33232357, 2020). "Expression of conjunctival MUC5AC and the squamous metaplasia in CIC are closely correlated with tear break up time as a dry eye severity indicator." (PMID 32873276, 2020). "We evaluated the dry eye-related quality-of-life score (DEQS), tear film breakup time (TBUT), fluorescein staining score, mRNA expression of MUC5AC and MUC16, MUC16 immunohistochemistry, and MUC5AC periodic acid Schiff (PAS) staining." (PMID 31614909, 2019). "In both SS and non-SS dry eye groups, a reduction in tear MUC5AC was observed, but the tear cytokine profile differed between the groups." (PMID 39408709, 2024). "Though no significant change in the protein level of MUC5AC was seen, lowered goblet cell density was seen post-vitreoretinal surgery indicating dry eye." (PMID 32437405, 2020). "Furthermore, we have previously reported two dry eye cases for which MUC5AC and MUC16 mRNA expression on the ocular surface was increased by the concomitant use of rebamipide and steroid ophthalmic suspensions, although the increase in MUC16 mRNA levels was lower than that of MUC5AC mRNA levels." (PMID 33232357, 2020).